TMEM167B (transmembrane protein 167B)
Description:
Involved in the early part of the secretory pathway.
Synonyms: C1orf119; AD-020; FLJ90710
Tractability: Antibody: UniProt predicts a signal peptide or a membrane-spanning region. PROTAC: ubiquitination databases record sites on it.
Gene: Protein-coding gene on chromosome 1 (109,090,367 to 109,096,935, forward strand). Ensembl gene ENSG00000215717.
Subcellular location: Golgi apparatus membrane
Gene Ontology:
Molecular function: protein binding
Biological process: constitutive secretory pathway
Cellular component: Golgi apparatus; Golgi membrane
Genetic constraint (gnomAD): Loss-of-function variants: 2 observed, 8.77 expected, observed/expected ratio (o/e) 0.23, 90% interval 0.092 to 0.72. That is too few expected variants to judge how well the gene tolerates losing a copy. Missense variants: 68 observed, 91.08 expected, observed/expected ratio (o/e) 0.75, 90% interval 0.61 to 0.91. Synonymous variants: 28 observed, 33.89 expected, observed/expected ratio (o/e) 0.83, 90% interval 0.61 to 1.13.
Homologues: Orthologues: chimpanzee TMEM167B (100% identical), pig TMEM167B (100% identical), rabbit TMEM167B (100% identical), guinea pig TMEM167B (99% identical), rat Tmem167b (99% identical), rat Tmem167b-ps1 (99% identical), zebrafish tmem167b (78% identical), dog TMEM167B (69% identical), Caenorhabditis elegans K07F5.22 (64% identical), tropical clawed frog tmem167b (64% identical). Paralogues in human: TMEM167A (42% identical).